FIS1 (fission, mitochondrial 1)
Diseases named in the same sentence as FIS1 in open-access papers (continued):
Sharing a sentence is not in itself a finding about the gene and the disease.
rhabdomyosarcoma (1 paper, 2025). A rare aggressive malignant mesenchymal neoplasm arising from skeletal muscle. "The minimal impact on sarcoma cell physiology, along with the up-regulation of fission adaptor proteins (MFF and FIS1) detected in rhabdomyosarcoma cells, suggests an alternative DRP1-independent mitochondrial fission mechanism that may efficiently compensate for the lack of DRP1 activity." (PMID 39643272, 2025). "Similar compensatory mechanisms might also be adopted by sarcoma cells, as evidenced by the up-regulation of the DRP1 adaptor proteins MFF and FIS1 in DRP1-depleted rhabdomyosarcoma RD cells, further suggesting that therapies targeting DRP1 for sarcoma may be likely to fail." (PMID 39643272, 2025). "In the rhabdomyosarcoma model, immunoblotting revealed up-regulation of the mitochondrial outer membrane adaptor proteins MFF and FIS1, which might contribute to alternative DRP1-independent mitochondrial fission." (PMID 39643272, 2025).
scrapie (1 paper, 2023). A fatal disease of the nervous system in sheep and goats, characterized by pruritus, debility, and locomotor incoordination. "In scrapie-infected mice, an imbalance in mitochondrial fusion and fission proteins such as Mfn1, Fis1, Mfn2, and Dlp1 was observed." (PMID 37569615, 2023).
squamous cell carcinoma (1 paper, 2023). A carcinoma arising from squamous epithelial cells. "Interestingly, the expression of some of those genes (TGM2, BNIP3, FIS1) has been linked as prognostic markers in squamous cell carcinomas." (PMID 38201216, 2023).
steatosis (1 paper, 2023). Increased lipid within the cytoplasm of cells. "Mfn1, Mfn2, and Opa1 mRNA expression in steatosis LO2 cells was also significantly lower, while the mRNA expression levels of Fis1 and Drp1 were much higher than those in the control (p < 0.01) and the taurine groups (p < 0.01)." (PMID 37373507, 2023). "The expression of FIS1 and DRP1 was also up-regulated in steatosis HepG2 cells." (PMID 37373507, 2023).
thyroid tumor (1 paper, 2015). A benign or malignant neoplasm affecting the thyroid gland. "The expression of mitochondrial fusion (Opa1, Mfn1 and Mfn2) and fission (Drp1 and Fis1) proteins were evaluated by immunohistochemistry (IHC) in a series of 88 human thyroid tumors." (PMID 25822260, 2015). "Indeed, both ex vivo and in vitro data also showed an overexpression of the fission proteins Drp1 and Fis1 in the oncocytic thyroid tumors histotype, favoring fission over fusion." (PMID 25822260, 2015). "Our data indicate that mitochondrial fission proteins Drp1 and Fis1 are overexpressed in oncocytic cell tumours, and that Drp1 expression levels correlates with oncocytic cell tumor malignancy ex vivo and with the migration ability of an oncocytic thyroid tumor cell line in vitro." (PMID 25822260, 2015).
tongue cancer (1 paper, 2020). A malignant neoplasm affecting the tongue. "Sirtuin 3 inhibition induces mitochondrial stress in tongue cancer by targeting mitochondrial fission and the JNK-Fis1 biological axis This suggests the importance of Fis1 mediated fission for maintenance of mitophagy both at rest and under stress." (PMID 33066461, 2020).
Zellweger syndrome (1 paper, 2021). "The expression level of FIS1 mRNA analyzed by qPCR was significant reduced (p = 0.015) in PEX26 deficient fibroblast of a patient with the severe phenotype of Zellweger syndrome (GM17398) as compared to a healthy fibroblast cell line." (PMID 34804114, 2021).
ZIKV infection (1 paper, 2025). "In contrast, ZIKV infection upregulated FIS1 expression in WT mice." (PMID 40313764, 2025). "FIS1, the key protein in mitochondrial fission decreased in Bmal1ECKO mice after ZIKV infection." (PMID 40313764, 2025).
α-synucleinopathy (1 paper, 2021). "Given the alterations in Drp1 levels in the TgA53TG2-3 models, we examined whether the expression of MFN1, OPA1, and Fis1 was altered as a function of α-synucleinopathy." (PMID 33924585, 2021).
cancer (24 papers, 2015 to 2025). A tumor composed of atypical neoplastic, often pleomorphic cells that invade other tissues. "In different types of cancer, including BC, it has been reported that increased mitochondrial fission is associated mainly with Drp1 and Fis1 proteins and decreased mitochondrial fusion, which has been associated with poor prognosis and cancer aggressiveness." (PMID 35327574, 2022). "Another mitochondrial fission regulator is FIS1, whose expression and activity was recently linked to the cancer phenotype, by several reports." (PMID 33233365, 2020). "More aligned with the idea that the ARCosome would suppress tumor growth, miR-484 downregulates Fis1 in cancer, associated with increased cancer resistance." (PMID 28603693, 2017). "Studies have shown that knockdown of FIS1 can reduce the sensitivity of tumor cells to cisplatin and reduce apoptosis of tumor cells, and FIS1 has the effect of inhibiting cancer." (PMID 39350223, 2024). "In the human non‐small cell lung adenocarcinoma cancer stem cell model A549‐SD, inhibiting the expression of FIS1 can inhibit mitochondrial division, thereby inhibiting mitophagy and consequently inhibiting the stemness of cancer stem cells." (PMID 34051059, 2021). "Increased Fis1 protein expression was reported in animal models of cancer cachexia together with mitophagy." (PMID 31466311, 2019). "Indeed, fission promoting proteins—including DRP1, MFF, FIS1, and MiD49 —are often found to have increased expression in cancer compared to normal adjacent tissues." (PMID 35356277, 2022). "Overall, these research studies indicated that not only DRP1, but also FIS1 could be considered as a valuable target for future therapeutic approaches against cancer." (PMID 33233365, 2020). "Fis1 is a receptor for dynamin-related protein 1 (Drp1) for the induction of mitochondrial fission that has been demonstrated to exhibit a key role in promoting the reprogramming of glucose metabolism and inducing the progression and anti-chemotherapy of cancer cells." (PMID 36922872, 2023). "To explore the hypothesis that dysregulated mitochondrial dynamics may impact drug sensitivity, we began by examining the alteration status of six canonical dynamics-regulating genes - OPA1, MFN1, MFN2, FIS1, MFF, and DNM1L (which encodes Drp1)—in human cancers." (PMID 29700304, 2018). "The miR-484 is a key regulator in common cancers and non-cancer diseases, targeting inflammation, apoptosis, and mitochondrial function-related mRNAs (SMAD7, Fis1, YAP1, etc.), and plays an important role in fighting disease." (PMID 37504299, 2023). "Our laboratory has also demonstrated that chronically elevated IL-6 can increase STAT3 activation and FIS-1 expression in myotubes and skeletal muscle independent of a cancer environment." (PMID 30918582, 2019). "Although early studies, using Fis1 overexpression and inhibition, support pivotal roles of Fis1 during mitochondrial fission, a follow‐up investigation in cancer cell lines shows that Fis1 deletion does not impair Drp1 recruitment and mitochondrial morphology (reviewed in detail by Chan, 2012)." (PMID 29968316, 2019). "Furthermore, conditional deletion of Fis1 in a carcinoma model did not lead to defects in mitochondrial fission, indicating that Fis1 is not essential for fission." (PMID 26793123, 2015). "However, in LO2 normal liver cells, the interaction between Met and Fis1 was weak and could not be regulated by Met kinase, indicative of the unique role of Met interaction with Fis1 in cancer." (PMID 34848680, 2021).
tumor (19 papers, 2018 to 2025). "Immunofluorescence analysis of the transplanted tumor cells using Ki-67 revealed that sh-FIS1 significantly suppressed tumor cell proliferation, whereas sh-MFF exhibited the opposite effect." (PMID 39350223, 2024). "Two recent studies used patient samples to determine potential changes of FIS1 during tumor progression." (PMID 35356277, 2022). "In our study, we found that DNM1L was highly expressed in tumor tissues, while Fis1 was low expressed." (PMID 36573240, 2022). "In gastric cancer, FIS1 mRNA expression was significantly higher in the primary tumor in comparison to matched normal adjacent tissue." (PMID 35356277, 2022). "In vivo, we performed a subcutaneous tumor transplantation assay in nude mice to determine the effect of Fis1 knockdown on tumorigenesis efficiency." (PMID 34051059, 2021). "One of these genes was associated with mitochondrial fission (fission 1, or FIS1), one with apoptosis (bcl-2 homologous antagonist killer, or BAK1) and one with tumor suppression (stratifin, or SFN)." (PMID 30404157, 2018). "We hypothesize that apart from its involvement as a receptor for DNM1L/DRP1 during mitochondrial division, MFF also interacts with FIS1 to contribute towards quality monitoring and prevention of tumor progression." (PMID 39350223, 2024). "However, following up-regulation of MFF, the expression levels of DNM1L/DRP1 and FIS1 were observed to decrease, thereby inhibiting tumor proliferation and progression." (PMID 39350223, 2024). "Furthermore, sh-DNM1L and sh-FIS1 significantly impeded the proliferation of GSCs, as well as reduced the number and volume of tumor spheres, along with diminishing the weight and size of heterotopic tumors." (PMID 39350223, 2024). "Therefore, our work provides closer insight into the indeterminate role of Fis1 protein, illuminating that Fis1 is particularly activated in tumor cells that are migrating and invading with large energy demands." (PMID 34848680, 2021). "Tumor formation was significantly reduced after Fis1 interference." (PMID 34051059, 2021). "Finally, we assessed the expression of Fis1 in the tumor specimens of the xenograft models." (PMID 36922872, 2023). "The OCR/ECAR, an indicator of tumor cell preference for glycolysis, increased following DNM1L up-regulation and decreased upon sh-FIS1." (PMID 39350223, 2024). "Together, our findings defined a central role of Met in activating Fis1 by tyrosine phosphorylation and promoting mitochondrial fission to facilitate HCC metastasis, suggesting its use in novel strategies to inhibit tumor recurrence and metastasis." (PMID 34848680, 2021). "Therefore, we conducted repeated interventions and related experiments in GSCs to investigate the impact of DNM1L/DRP1, FIS1 and MFF expression on tumor progression in different metabolic models." (PMID 39350223, 2024). "The molecular processes of mitochondrial dynamics are governed by MFN2 (mitofusin 2), OPA1 (optic atrophy 1), FIS1 (mitochondrial fission 1), and DRP1 (dynamin-related protein 1), which are overexpressed in tumour cells and crucial for the development of the malignant phenotype." (PMID 35008887, 2021). "Furthermore, increased FIS-1 expression in cachectic skeletal muscle from tumor-bearing mice is dependent on IL-6; tumor-bearing mice treated with an IL-6 receptor antibody demonstrated an attenuation of muscle STAT3 and FIS-1 expression." (PMID 30918582, 2019). "Immunohistochemistry analysis showed that p-Fis1 and HGF were expressed at higher levels in tumor tissues compared to adjacent non-tumorous tissue." (PMID 34848680, 2021).
infection (8 papers, 2017 to 2024). The state of being infected such as from the introduction of a foreign agent such as serum, vaccine, antigenic substance or organism. "In contrast, at the late stage of infection, EPEC stimulates mitochondrial fragmentation via an EspH-dependent increase in FIS1 levels and causes a loss in ΔΨm,40 leading to host cell death, which likely facilitates pathogen dispersal." (PMID 38356294, 2024). "To interrogate the specific role of FIS1 in infection-induced mitophagy, we assessed the impact of ΔespZ on FIS1-depleted cells." (PMID 36476073, 2022). "In the early stages of infection, EspZ interacts with FIS1 and blocks its action, thereby protecting the host mitochondrial network and consequently, enhancing host cell viability." (PMID 36476073, 2022). "Later in infection, however, EspH-dependent increase in FIS1 results in significant mitochondrial fragmentation and host cell death; this likely facilitates pathogen dispersal." (PMID 36476073, 2022). "Infection of epithelial cells with either wildtype EPEC or an isogenic espZ deletion mutant (ΔespZ) robustly upregulated FIS1 abundance, but a marked increase in mitochondrial fragmentation and mitophagy was seen only in ΔespZ-infected cells." (PMID 36476073, 2022). "The occurrence of a macromolecular assembly (through proteins such as MED30 and NDUFB11) and cellular localization (through proteins such as FIS1) seems to occur as part of the 48-h post-infection pattern, thereby suggesting that the cells experience enormous energy expenditure." (PMID 38087340, 2023). "This does not seem surprising since our previous work indicated that the level of Fis1 elevated at the late stages of infection with ECTV in L929 cells, providing the opportunity for close contact between MAVS and Fis1." (PMID 39338909, 2024). "Infection of C2BBe cells with the corresponding mutants showed that, like WT EPEC, Δmap and ΔespF upregulated FIS1 levels relative to mock-treated cells." (PMID 36476073, 2022). "Although SS-31 has been shown to interact with the inner mitochondrial membrane to modulate electron flux, increase ATP generation, and decrease ROS production, the alteration in FIS1 due to infection appears not to be rescued by SS-31." (PMID 38860823, 2024). "However, calcitonin downregulated the levels of Drp1 and Fis1 in the prefrontal cortical tissues of CKD mice, while the Drp1 expression was rescued following infection with AAV expressing Drp1 without affecting that of Fis1." (PMID 36050772, 2022).
neurodegenerative disease (7 papers, 2014 to 2024). A disorder of the central nervous system characterized by gradual and progressive loss of neural tissue and neurologic function. "The SOD1, SOD2, and FIS1 genes of yeast cells are homologous to those in humans, and mutation or change of expression of these genes in humans is related to neurodegenerative diseases." (PMID 36829855, 2023). "Our previous work identified a specific Drp1-Fis1 inhibitor, P110, and showed that Fis1 recruits Drp1 under cell stress in numerous neurodegenerative disease models; inhibition of the Fis1-Drp1 interaction has therapeutic benefits in these models." (PMID 30232469, 2018). "FIS1 (fission 1 (mitochondrial outer membrane) homolog (S. cerevisiae)) has been well established in the etiology of neurodegenerative diseases, and commonly regarded as mitochondrial fission inducer and promoting cell apoptosis." (PMID 24416201, 2014). "Delineating the causative factor and sequential consequences of STX17-initiated mitophagy, regulated by Fis1, may lead to greater insights into interventions on diseases, particularly for therapeutics on neurodegenerative diseases." (PMID 31053718, 2019).
Kidney Disease (4 papers, 2021 to 2025). "Studies have shown that the expression of mitochondrial dynamic proteins, Drp1 and Fis1, are upregulated, while Mfn1 expression is down-regulated in early-stage renal disease." (PMID 33902473, 2021). "The results indicate that abnormal mitochondrial dynamics may participate in CIH-induced kidney disease progression, and the expression of p66Shc, Fis1 and Mfn1 is closely related to disease severity." (PMID 33902473, 2021). "From comparisons of AGO2-IP RNAs, besides Fis1 encoding the mitochondrial fission protein FIS122–24, we also examined other candidate targets of miR-379 with putative functions related to kidney disease." (PMID 33398021, 2021). "Therefore, using drugs targeting FIS1 and DRP1 is important in improving kidney disease." (PMID 36499050, 2022).
heart disease (3 papers, 2015 to 2022). "However, other recent papers have shown the efficacy of a molecule able to inhibit the interaction DRP1/FIS1, which blocks pathological or excessive mitochondrial fragmentation seen in ALS and cardiac diseases without affecting basal mitochondrial fission." (PMID 33330472, 2020).
kidney (2 papers, 2023 to 2024). "In vitro and in vivo experiments have evidenced that the incorporation of lactate can facilitate the lactoacylation of Fis1 lysine 20 (Fis1 K20la), which in turn induces excessive mitochondrial fission and dysfunction, thereby exacerbating kidney injury." (PMID 39683818, 2024).
metabolic disease (2 papers, 2022). A congenital disorder (due to inherited enzyme abnormality) or acquired (due to failure of a metabolically important organ) disorder resulting from an abnormal metabolic process. "The proof-of-principle study presented in the current work demonstrates the possibility of developing small molecules targeting the Fis1-Atf5 axis of ISR to treat metabolic diseases." (PMID 35015731, 2022). "Collectively, these results support the potential use of small molecules targeting the Fis1-Atf5 axis, such as MMF, to treat metabolic diseases." (PMID 35015731, 2022).
neurological disorders (1 paper, 2021). "This review presents current perspectives on the emerging functions of Fis1 and their implications in human health and diseases, with an emphasis on Fis1's role in both endocrine and neurological disorders." (PMID 33841340, 2021).
FIS1 also shares sentences with these, for which no sentence is quoted: Insulin resistance (6 papers); myocardial infarction (4); cardiovascular diseases (3); gastric cancer (2); glioblastoma (2); adenocarcinoma (1); Atrophy (1); benign tumors (1); cardiac arrest (1); centronuclear myopathy 1 (1); Cerebral ischemia (1); chronic kidney disease (1); Cognitive impairment (1); Crohn disease (1); delirium (1); Encephalopathy (1); fatty liver disease (1); fungal infection (1); gastric tumour (1); head and neck squamous cell carcinoma (1); Hyperammonemia (1); Hypertension (1); ischemia reperfusion injury (1); liver disease (1); liver fibrosis (1); lung squamous cell carcinomas (1); lupus nephritis (1); male infertility (1); membranous nephropathy (1); metastatic prostate carcinoma (1).
A further 13 diseases each share a sentence with FIS1 in 1 paper.